HNRNPL (heterogeneous nuclear ribonucleoprotein L)
Diseases named in the same sentence as HNRNPL in open-access papers (continued):
Sharing a sentence is not in itself a finding about the gene and the disease.
cancer (54 papers, 2009 to 2025). A tumor composed of atypical neoplastic, often pleomorphic cells that invade other tissues. "CASC9 (circulating cancer susceptibility 9) forms a functional cytoplasmic complex with HNRNPL (heterogeneous nuclear ribonucleoprotein L) that regulates AKT function." (PMID 34071216, 2021). "HNRNPK and HNRNPL belong to the heterogeneous nuclear ribonucleoprotein family and interact with tumor-associated lncRNAs to regulate the tumorigenesis and progression of various cancers, including HCC." (PMID 36289466, 2022). "Increased hnRNPL expression might lead to decreased degradation of the Bcl-2 mRNA, which causes cancer." (PMID 34333526, 2021). "Among the AS regulators with altered activity in cancer cells, heterogeneous nuclear ribonucleoprotein L (hnRNPL) has been largely described, initially as a splicing factor, then, more recently, as a regulator of RNA transcription and stability." (PMID 40702809, 2025). "Inhibition of HNRNPL can destabilizeYY1 mRNA and enhance T cell-mediated cancer cell ferroptosis in castration-resistantprostate cancer." (PMID 41259792, 2025). "Upregulated HMGA2 not only boosts cancer stemness but also enhances HNRNPL activity, which in turn promotes circFAM73A biogenesis to build up a positive feedback loop." (PMID 39550559, 2024). "Disruptions of the splicing machinery of HNRNPL emerge as a potential approach to inhibiting cancer progression." (PMID 39550559, 2024). "To our knowledge, we firstly demonstrated that hnRNPL exerts an important role in the cancer development via post-transcriptional modifications." (PMID 35982900, 2022). "HnRNPL knockout effectively downregulates PD-L1 and restores the cancer cell sensitivity to T cell killing in vitro and in vivo." (PMID 36335094, 2022). "Ferroptosis functions remarkably in T cell-driven adverse outcomes of cancer cells, and HnRNPL inhibits Jurkat T cell-mediated Castration-Resistant Prostate Cancer (CRPC) cell ferroptosis through the YY1/PD-L1 axis, partially promoting cancer immune escape." (PMID 36335094, 2022). "In several kinds of hnRNPL overexpressing cancers, hnRNPL acts as an intron splicing factor that interacts with CA repeats in the 3′ untranslated region (UTR) of the Bcl-2 mRNA to prevent its degradation." (PMID 34333526, 2021). "Linked to our results, we demonstrated that the binding of SNHG1 to hnRNPL is responsible for a part of its cancer-promoting features in PCa." (PMID 33542227, 2021). "Future study is warranted to elucidate the targets and pathways regulated by the HNRNPL‐circARHGAP35‐TFII‐I axis in cancers." (PMID 34258149, 2021). "IPO8, PUM1 and HNRNPL were among the three most stable genes for our set of cancer cell lines and also for all cell lines investigated." (PMID 34593877, 2021). "For our set of cancer cell lines, HNRNPL was found to be the most stable reference gene as determined by all evaluation methods consistently." (PMID 34593877, 2021). "The mutation of TRBP results in abnormal expression of miRNA, and cancer cell proliferation and differentiation; HnRNPL is also a multifunctional RBP that interacts with long non-coding RNA (lncRNA) in different cancers." (PMID 32653017, 2020). "This analysis revealed that HNRNPL was involved in many crucial pathways and was correlated with cancer." (PMID 31355266, 2019). "It is interesting to note that miR-155 is an essential microRNA during inflammation, as was also evidenced for HNRNPL and cellular aneuploidy, suggesting our finding as a novel dynamic molecular link between inflammation and cancer." (PMID 31018621, 2019). "Previous studies have reported that hnRNPL is involved in mRNA splicing, embryonic development and cancer metastasis." (PMID 31856843, 2019). "Fbxo16 could therefore acts as the substrate-recognizing receptor for several proteins involved in cell proliferation, including β-catenin, hnRNPL and NF-κB p65, promotes their degradation and prevents cancer progression." (PMID 40529355, 2025).
cancer (continued). "Apart from HNRNPL, other hnRNP members are also proven as circRNA regulators in cancer." (PMID 39550559, 2024). "Among hnRNP family members, HNRNPL is most frequently implied in circRNA alteration in cancers." (PMID 39550559, 2024). "In addition, SNHG1 regulated the translation pathway of E-cadherin by reducing the expression of hnRNPL to promote the metastasis of cancer cells." (PMID 36087568, 2022). "In contrast, IPO8, PUM1 and—in case of cancer cell lines—HNRNPL showed the lowest variation." (PMID 34593877, 2021). "Among the most representative candidate cancer driver genes are HNRNPL, KLF5, and TFDP1." (PMID 31925297, 2020). "Pan‐cancer genetic alternations of hnRNP genes indicated that the overall average mutation frequency ranged from 0% to 14.9%, and hnRNP genes including HNRNPM, HNRNPUL1, HNRNPL showed high mutation frequencies." (PMID 32915499, 2020). "Previous reports indicated that hnRNPL played critical roles in cancer progression." (PMID 31856843, 2019). "Previous study has revealed that ebv-sisRNA-1 and ebv-sisRNA-2 interact with human HNRNPL and HNRNPD proteins, probably implicating in the pro-cancer-related phenotypes." (PMID 40579704, 2025). "Overall these results indicate not only that our approach efficiently defines already established cancer-related genes, but, more importantly, that it can predict novel cancer hubs, e.g. TGOLN2, HNRNPL, and NHRNPU." (PMID 39657701, 2024). "SNHG1 interacting with proteins, such as hnRNPL, EZH2, and MART3, to modulate tumor progression have been reported in various cancer types." (PMID 36130928, 2022). "In conclusion, we propose the use of IPO8, PUM1, HNRNPL, SNW1 and CNOT4 as reference genes in studies comparing gene expression between different cancer and/or normal cell lines." (PMID 34593877, 2021). "We finally obtained eight bona fide cancer driver genes, including CEP57, HNRNPL, KLF5, OXA1L, PAFAH1B1, RBM39, SYT13, and TFDP1." (PMID 31925297, 2020). "Based on previous observations, we provide a strong evidence that SNHG1 interacts with RNA-binding protein hnRNPL to activate EMT pathway, promoting the malignant progression of PCa, which is expected to provide a comprehensive understanding of the way SNHG1 acts on cancers." (PMID 33542227, 2021). "In addition, we noticed seven of them have been included in the latest version of The Network of Cancer Genes35 (KLF5, OXA1L, RBM39, and TFDP1) or CancerMine36 (HNRNPL, KLF5, PAFAH1B1, SYT13, TFDP1), two manually curated cancer gene databases, further confirming our findings." (PMID 31925297, 2020).
tumor (40 papers, 2013 to 2025). "We further tested the correlation of HNRNPL protein expression and clinical pathologic data and suggested that HNRNPL was associated with tumor invasion of PC." (PMID 31355266, 2019). "Aberrant expression of HNRNPL and its RNA target are closely associated with the proliferation, invasion and metastasis of tumor cells (Kedzierska & Piekielko-Witkowska, 2017; Geuens, Bouhy & Timmerman, 2016)." (PMID 31844595, 2019). "SFs HNRNPH3 and HNRNPL were overexpressed in tumor samples and were signifcantly associated with the OS of HCC patients." (PMID 31844595, 2019). "In addition, the mRNA level of HNRNPL was determined to positively associate with tumor invasion and advanced clinical stage." (PMID 31355266, 2019). "Here, the authors carry out a systematic review of lncRNAs in breast cancer and show that DSCAM-AS1 is highly expressed in oestrogen receptor positive tumours and enhances cancer through an interaction with hnRNPL; and is also associated with tamoxifen resistance." (PMID 27666543, 2016). "Forced expression of Fbxo16 in tumor cell lines inhibited cell growth, whereas knockdown of Fbxo16 in these cells resulted in increased β-catenin and hnRNPL protein levels and enhanced tumor cell proliferation." (PMID 40529355, 2025). "To further elucidate the role of HNRNPL in mediating metastasis via ITGβ3, we explored its capacity to regulate tumor-platelet clusters." (PMID 40060410, 2025). "Regarding Fbxo16, previous reports showed that it mediates polyubiquitination and degradation of β-catenin and heterogeneous nuclear ribonucleoprotein L (hnRNPL), both of which regulate signaling pathways leading to cell proliferation and tumor progression." (PMID 40529355, 2025). "PTBP1, also known as hnRNPL, is mainly involved in the regulation of gene transcription, mediating the regulation of alternative splicing events in tumor invasion-related genes." (PMID 38071681, 2024). "hnRNPL promotes various biological processes of tumor cells, including proliferation, migration and invasion by regulating various tumor-related signal pathways." (PMID 34333526, 2021). "Heterogeneous nuclear ribonucleoprotein L (hnRNPL) is a type of RNA binding protein that highly expressed in a variety of tumors and plays a vital role in tumor progression." (PMID 34333526, 2021). "In this context, HNRNPL interacts with various lncRNAs (specific lncRNAs dependent on tumor type) to promote tumorigenesis." (PMID 34543262, 2021). "hnRNPL promotes various biological processes of tumor cells, including proliferation, clonogenic survival, and invasion." (PMID 34333526, 2021). "We observed that E2F3 promoter activation was suppressed in RBAT1 or HNRNPL knockdown tumor cell lines." (PMID 32669100, 2020). "HNRNPL was also correlated with pathological grade, and the higher the HNRNPL expressed, the higher the pathological grade of the neoplasm." (PMID 31355266, 2019). "The only reported protein that directly interacts with DSCAM‐AS1 is hnRNPL, which mainly exists in the cytoplasm to promote tumor invasion." (PMID 30430768, 2018). "To confirm the impact of hnRNP-L depletion on tumor growth in vivo, we established a subcutaneous xenograft tumor model in athymic nude mice by injecting EJ-sh-hnRNPL cells and control EJ-NC cells." (PMID 28088793, 2017). "We demonstrate that DSCAM-AS1 mediates tumour progression and tamoxifen resistance and identify hnRNPL as an interacting protein involved in the mechanism of DSCAM-AS1 action." (PMID 27666543, 2016). "In order to determine the role of hnRNPL in tumor progression, we designed shRNA to specifically deplete hnRNPL expression PANC-1 cells." (PMID 27689400, 2016). "Next, we examined the capability of tumor formation and anchorage-independent growth after knocking-down hnRNPL in uc.345 overexpressing PANC-1 cells." (PMID 27689400, 2016).
tumor (continued). "With advancements in technologies that capture circulating tumor cells, we propose that quantifying expression of HNRNPL and its circular RNA derivatives may be an effective biomarker of recurrence in TNBC patients given radiotherapy." (PMID 40060410, 2025). "Importantly, hnRNPL ΔRRM3 mutant obviously promoted tumor growth in vivo in a xenograft mouse model." (PMID 34333526, 2021). "hnRNPL is also highly expressed in a variety of tumors and plays a vital role in tumor progression." (PMID 34333526, 2021). "Our data support the hypothesis of a “tuning CIN to optimize tumor fitness” by elucidating a novel molecular mechanism that highlight the role of the RNA binding protein HNRNPL as the tiebreaker for the miR-155 targeting of BUB1." (PMID 31018621, 2019). "In addition to the mRNA level, HNRNPL protein expression was proven to be correlated with tumor pathologic grade and invasion." (PMID 31355266, 2019). "We further identified that the high expression of HNRNPL was a powerful and independent predictor of poor patient outcome, indicating that HNRNPL mRNA level could offer potential value for early diagnosis of PC and tumor monitoring after surgery." (PMID 31355266, 2019). "Mechanistic investigations demonstrated that 345 could promote tumor growth via an upregulating the hnRNPL expression." (PMID 27689400, 2016). "Moreover, RBAT1 may activate E2F3 and interact with HNRNPL to promote tumor progression." (PMID 37501162, 2023). "Further experiments demonstrated that SNHG1 can interact with hnRNPL and ultimately leads to down-regulation of E-cadherin expression and promote EMT progression, leading to tumor metastasis in PCa." (PMID 33542227, 2021). "Mechanistically, we showed that RBAT1 recruits the HNRNPL protein to E2F3 promoter region, which activates E2F3 signaling to prime for tumor cell proliferation." (PMID 32669100, 2020). "The top two counterpart SFs were HNRNPL and HNRNPH3, and the expression of HNRNPL and HNRNPH3 in tumor sample were significantly higher than adjacent normal sample." (PMID 31844595, 2019). "Compared to adjacent normal sample, the expression of HNRNPL and HNRNPH3 were higher in tumor sample." (PMID 31844595, 2019). "All antigens, and particularly EZR, VCL, VIM, PDC6I, hnRNPL and ANXA2 induced a specific antibody response in KC and KPC already at 1 to 3 months of age, when the tumor stage was limited to early PanIN." (PMID 24010981, 2013). "Importantly, only HNRNPL was found to bind specifically to RBAT1 in both protein subsets, and these results were confirmed by western blot analysis in three tumor cell lines." (PMID 32669100, 2020). "To determine whether RBAT1 could activate E2F3 by recruiting HNRNPL to its promoter, we evaluated the status of E2F3 promoter transcriptional activity in tumor cell lines with different RBAT1 and HNRNPL expression levels using luciferase assays." (PMID 32669100, 2020). "Moreover, we observed HNRNPL was significantly upregulated in HCC compared to matched non‐tumor (NT) liver tissues, and is positively correlated with circARHGAP35 but not linear ARHGAP35 in HCC tissues and cells." (PMID 34258149, 2021).
infection (4 papers, 2017 to 2024). The state of being infected such as from the introduction of a foreign agent such as serum, vaccine, antigenic substance or organism. "Expectedly, in the very early stages of infection, proteins involved in translation, transcription and DNA condensation were upregulated, notably HIST1H1E, HNRNPL, PRRC2A and TRIM28." (PMID 31315557, 2019). "Among the 14 hits, depletion of ILF2, ILF3, heterogeneous nuclear ribonucleoprotein L (HNRNPL), and STAU1 significantly decreased EBOV-eGFP infection for each siRNA used." (PMID 30301857, 2018).
brain disorder (1 paper, 2022). A disease affecting the brain or part of the brain. "HNRNPL has been found to participate in regulating brain disorders." (PMID 35549989, 2022).
HNRNPL also shares sentences with these, for which no sentence is quoted: pulmonary fibrosis (6 papers); idiopathic pulmonary fibrosis (3); autoimmune disease (2); glioblastoma (2); non-small cell lung carcinoma (2); Sepsis (2); anemia (1); antiphospholipid syndrome (1); Azoospermia (1); B cell lymphomas (1); Cerebral ischemia (1); chronic myeloid leukemia (1); chronic obstructive pulmonary disease (1); Cognitive impairment (1); dengue (1); diffuse large B-cell lymphoma (1); epilepsy (1); esophageal cancer (1); genetic diseases (1); head and neck cancer (1); head and neck squamous cell carcinoma (1); hyperprolactinemia (1); intestinal cancer (1); lymph node metastases (1); melanoma (1); multiple myeloma (1); muscular dystrophy (1); myotonic dystrophy (1); neutropenia (1); non-Hodgkin lymphoma (1).
A further 7 diseases each share a sentence with HNRNPL in 1 paper.